RNU1-119P (RNA, U1 small nuclear 119, pseudogene)
Gene: Small nuclear RNA gene on chromosome 15 (44,884,616 to 44,884,780, forward strand). Ensembl gene ENSG00000212424.
Homologues: Orthologues: chimpanzee U1 (95% identical), macaque U1 (90% identical), macaque U1 (87% identical). Paralogues in human: RNU1-78P (99% identical), RNU1-89P (88% identical), RNU1-1 (87% identical), RNU1-2 (87% identical), RNU1-27P (87% identical), RNU1-28P (87% identical), RNU1-3 (87% identical), RNU1-4 (87% identical), RNU1-83P (87% identical), RNVU1-18 (87% identical), RNVU1-29 (87% identical), U1 (87% identical), and 134 more.